MMP9 (matrix metallopeptidase 9)
Diseases named in the same sentence as MMP9 in open-access papers (continued):
Sharing a sentence is not in itself a finding about the gene and the disease.
pulmonary edema (6 papers, 2014 to 2021). Accumulation of fluid in the lung tissues causing disturbance of the gas exchange that may lead to respiratory failure. "MMPs, in particular MMP-9, is involved in the pathogenesis of various pulmonary inflammatory diseases and associated with pulmonary edema." (PMID 31447768, 2019). "It has been observed that MMP-2 and MMP-9, two most crucial MMPs in the lung are over-expressed in pulmonary edema, suggesting that MMPs may become a potential target for pulmonary edema treatment." (PMID 34163357, 2021). "BBG administration decreased mature interleukin-1β, myeloperoxidase, and matrix metallopeptidase-9 activation, but increased tight junction proteins, such as ZO-1 and occludin, which ameliorated pulmonary edema via anti-inflammation and improved neurological deficits." (PMID 24533168, 2014).
sarcoidosis (6 papers, 2015 to 2025). Sarcoidosis is a multisystemic disorder of unknown cause characterized by the formation of immune granulomas in involved organs. "We have also demonstrated that sarcoid AMs per se produce elevated levels of metalloproteinase (MMP)-9, a molecule belonging to a family of extracellular and cell surface-associated proteinases, implicated in tissue homeostasis, host defence and tissue repair also in sarcoidosis." (PMID 26240517, 2015). "Previous studies have demonstrated the contribution of gelatinase MMP-2 and MMP-9 in cell migration, and we explored the role of MMP-9 in macrophage recruitment in GA and sarcoidosis." (PMID 36959923, 2023). "In summary, MMP-9 and pSTAT1 showed differential expressions in GA and sarcoidosis, especially with regard to MMP-9 in elastic fibers." (PMID 36959923, 2023). "In sarcoidosis patients, MMP-9 (R = −0.7127, P = 0.0009) and pSTAT1 (R = −0.5604, P = 0.0067) were found to show stronger expressions in lesions with less lymphocyte infiltration." (PMID 36959923, 2023). "Results from hematoxylin and eosin (H&E) staining and IHC staining of MMP-9 and pSTAT1 within the skin lesions of GA and sarcoidosis were analyzed, and random forest was applied for developing a predictive model." (PMID 36959923, 2023). "Significantly greater expressions of MMP-9 (especially in elastic fibers, EFs, P < 0.0001) and pSTAT1 (P = 0.0003) were observed in lesion samples of GA versus sarcoidosis patients." (PMID 36959923, 2023). "Herein, we aim to compare the histological features and investigate the expression of MMP-9 and pSTAT1 between GA and sarcoidosis." (PMID 36959923, 2023). "A lot of potential targets of the RBPs, including MMP-9, have already been reported to be dysregulated in sarcoidosis." (PMID 27575817, 2016). "The MMP-9 high levels characterizing AMs from patients with active sarcoidosis paralleled the reduced mRNA amounts of its major inhibitor, TIMP-1." (PMID 26240517, 2015). "Panel a, BAL fluids from patients with active sarcoidosis were characterized by a stronger MMP-9 activity (12.5 ± 5.8) as compared to those obtained from inactive sarcoidosis (3.6 % ± 1.3; p < 0.05)." (PMID 26240517, 2015). "AM and T cell subset isolation demonstrated that the source responsible of MMP-9 activity was represented by AMs (2.8 ± 0.35 and 22.5 ± 3.8 in AMs from inactive and active sarcoidosis, respectively; p < 0.01 vs active disease)." (PMID 26240517, 2015). "Since IFN-γ is one of the prevalent cytokines in the lung of patients with active sarcoidosis, by gelatin zymography assays we evaluated MMP-9 activity in the lung of our patients." (PMID 26240517, 2015). "Moreover, we also found that MMP-9 staining in elastic fibers showed the best efficiency in distinguishing GA versus sarcoidosis as predicted by the model." (PMID 36959923, 2023). "Here, we found that in sarcoidosis, pSTAT1 was positively correlated with MMP-9, suggesting that pSTAT1 may promote granulomatous fibrosis by inducing the expression of MMP-9 after the effector phase." (PMID 36959923, 2023). "These included MMP9, a matrix metalloproteinase strongly associated with lung injury and fibrosis, and NOTCH4, an important regulator of inflammation and lung remodeling previously implicated in sarcoidosis." (PMID 36388923, 2022). "MMP9 expression was increased more than 30-fold in sarcoidosis tissues." (PMID 36388923, 2022). "The increasing of MMP-9 production induced by TL1A on sarcoid AMs might exacerbate these phenomenas contributing to the evolution of sarcoidosis towards its irreversible phase." (PMID 26240517, 2015). "Interestingly, TL1A and DR3 stimulation was able to increase the production of MMP-9 by AMs of patients with inactive sarcoidosis, while macrophages derived from the lung of patients with the active form of the disease did not vary MMP-9 production after TL1A stimulation." (PMID 26240517, 2015).
sarcoidosis (continued). "Eight upregulated transcripts were common to sarcoidosis lung granulomas (CSF3, SERTAD1, MMP9, CCL19, BCL3, AREG, PTGS, F3)." (PMID 33276795, 2020). "In contrast to PCBP2, the mRNA expression of other RBPs and two inhibitors of MMP-9 (RECK and PTEN) did not correlate with any BA sub-population in our patients with sarcoidosis." (PMID 27575817, 2016).
sarcopenia (6 papers, 2016 to 2026). Progressive decline in muscle mass due to aging which results in decreased functional capacity of muscles. "Increased expression of MMP-2 and MMP-9 is seen in a variety of diseases associated with sarcopenia, and this increase may be associated with muscle fiber regeneration and tissue inflammation." (PMID 40309438, 2025). "Another study evaluating serum MMP9 levels in 88 sarcopenic patients aged 65 and over showed that serum MMP9/tissue inhibitor of metalloproteinase 1 (TIMP1) had similar performance as a sarcopenia biomarker to the SARC-F questionnaire (AUC = 0.67)." (PMID 40008206, 2024). "Empagliflozin, a sodium-glucose co-transporter 2 inhibitor, may inhibit sarcopenia-induced skeletal muscle fibrosis and improve skeletal muscle function through the AMPKα/MMP-9/TGF-β1/Smad pathway." (PMID 40309438, 2025). "Although MMP-2 and MMP-9 seem to play major roles in the degradation of the extracellular matrix that leads to muscle wasting, the pathophysiological relevance of MMP-7 in the development and progression of sarcopenia is still mostly unknown." (PMID 32375664, 2020). "Although this implies there could be common defects in ALS and sarcopenia, in old mice the OPN-high/MMP-9-high MNs were negative for ER-stress markers, which suggests simple co-expression of OPN and MMP-9 does not necessarily induce neurodegeneration." (PMID 27264390, 2016).
Trichiasis (6 papers, 2006 to 2018). Inversion and rubbing of the eyelashes against the globe of the eye. "MMP9 Q279R AG heterozygotes were most protected from risk of trichiasis when this genotype was combined with the CSF2_27348 TT genotype (OR, (95%CI) = 0.41 (0.25, 0.66)." (PMID 20015396, 2009). "In contrast MMP9 Q279AG/CSF2_27348 AA conferred increased risk of trichiasis (OR, (95%CI) = 7.55 (1.01, 56.71) with wide confidence intervals resulting from the small number of subjects with the CSF2_27348 AA genotype." (PMID 20015396, 2009). "The present study found a coding SNP (Q279R in exon 6) within the MMP9 gene to be associated with a lowered risk of trachomatous scarring and trichiasis, which was more marked for trichiasis." (PMID 16643654, 2006). "This identified a variety of pro-inflammatory (IL1B, TNFA, S100A7, CXCL5, NOS2A) and tissue remodelling factors (MMP7, MMP9 and MMP12), which were associated with conjunctival scarring and trichiasis before surgery." (PMID 23285311, 2012). "In individuals with trachomatous scarring and/or trichiasis, factors involved in innate pro-inflammatory responses and matrix remodeling (IL1B, CXCL5, S100A7, CTGF, MMP7, and MMP9) were upregulated." (PMID 28966918, 2017).
/T cell lymphoma (5 papers, 2007 to 2022). "HG T-cell lymphomas showed higher VEGF-A mRNA expression compared with LG T-cell lymphomas and moreover the mRNA VEGF-A results were correlated with MMP-9 results in T-cell lymphomas." (PMID 23641796, 2013). "MMP-9 results in CLBL-1 and OSW cells additionally confirmed the different MMP-9 expression both at the mRNA and protein level in B- and T-cell lymphomas." (PMID 23641796, 2013). "Almost all of the patients with nasal NK/T cell lymphoma and anaplastic large-cell lymphoma expressed MMP9." (PMID 18093334, 2007). "Cells which expressed MMP-9 existed at the invasive edge of tumor cell nests and the peripheral regions of the necrotic zone in nasal NK/T cell lymphomas." (PMID 18093334, 2007). "We found that most patients with nasal NK/T cell lymphoma expressed high levels of MMP-9." (PMID 18093334, 2007). "In this study, 15 of 17 (88%) patients of nasal NK/T cell lymphoma expressed MMP9." (PMID 18093334, 2007). "MMP9 and TIMP1 expression is significantly upregulated in canine T-cell lymphomas, and was upregulated in both Ema and TL-1 cells." (PMID 27639374, 2016). "Significant correlations between MMP-2 and TIMP-2 (p<0.001; Spearman r=0.82) and between MMP-9 and VEGF-A (p<0.01; Spearman r=0.67) were found in T-cell lymphomas." (PMID 23641796, 2013). "Moreover, MMP-9, MT1-MMP, TIMP-1 and VEGF-A were expressed at the highest levels in high-grade T-cell lymphomas." (PMID 23641796, 2013). "Overall, this experimental evidence supports the hypothesis that MMP-9 and TIMP-1 may act in concert in canine T-cell lymphoma." (PMID 23641796, 2013). "A positive correlation was found between MMP-9 and VEGF-A in T-cell lymphomas." (PMID 23641796, 2013). "Interestingly, higher MMP-9, MT1-MMP, VEGF-A, VEGF-164 and TIMP-1 mRNA expressions were observed in HG T-cell lymphomas compared to LG T-cell lymphomas, although the differences were not statistically significant." (PMID 23641796, 2013). "The expression of P-glycoprotein and MMP-9 was evaluated in the 20 patients with nasal NK/T-cell lymphoma and 25 with nasal non-NK/T-cell lymphoma and the relationship between expression of these proteins and clinical results were analyzed in this report." (PMID 18093334, 2007). "Distant involvement free 5-year survival rates for patients with MMP-9 negative, and MMP-9 positive in T cell lymphomas were 89%, and 57%, respectively." (PMID 18093334, 2007). "Although the role of strong MMP-9 expression in the spread of nasal NK/T cell lymphoma has yet to be definitely established, our findings demonstrated that MMP-9 may be related to a strong tendency to metastasize and the locally destructive nature of nasal NK/T cell lymphoma." (PMID 18093334, 2007).
adenoid cystic carcinoma (5 papers, 2012 to 2022). A malignant tumor arising from the epithelial cells. "Materials and Method: Using an ELISA kit, the circulating levels of MMP-9 in sera from 58 patients with salivary gland tumor (31 pleomorphic adenoma, 17 adenoid cystic carcinoma and 10 mucoepidermoid carcinoma) and 30 healthy controls was assessed." (PMID 25469360, 2014). "Moreover, in vitro silencing of MMP9 decreased the migratory activity in Adenoid Cystic Carcinoma cells." (PMID 32445177, 2020). "Here, we demonstrated that WIP1 silencing reduced MMP-9 and VEGF-C expression as well as migration and invasion of salivary adenoid cystic carcinoma (ACC) cells." (PMID 25797250, 2015). "In clinical adenoid cystic carcinoma patients, higher EBP1 expression was positively correlated with E-cadherin levels (P<0.001) but negatively correlated with MMP9 expression (P=0.0002)." (PMID 23110497, 2012). "We performed immunohistochemical analysis on 132 primary adenoid cystic carcinoma and adjacent non-cancerous tissues using commercial EBP1, MMP9, E-cadherin and ICAM-1 antibodies." (PMID 23110497, 2012).
bone metastasis (5 papers, 2018 to 2022). Transfer of a neoplasm from its primary site to bones. "Expression of cyclin D1 was significantly associated with distant metastatic relapse, latent bone metastasis, ER expression, PR expression, and MMP9 expression." (PMID 29416639, 2018). "This study identified 74 DEGs between BRCA samples with or without bone metastasis, and 5 important DEGs were finally filtered, namely, MMP9, ITGB3, BMP2, CCL2, and PROM1." (PMID 36193308, 2022).
cerebral amyloid angiopathy (5 papers, 2020 to 2023). "On the other hand, GM6001 and another MMP inhibitor, minocycline, were reported to efficiently reduce upregulated MMP-2 and MMP-9 and prevent inflammation and oxidative stress associated with cerebral amyloid angiopathy in AD mice." (PMID 33986628, 2021).
cervical tumor (5 papers, 2012 to 2024). "Several lines of evidence indicate that MMP-9 plays an important role in cervical tumor development." (PMID 22438955, 2012). "Subsequently, we verified the promotional effect of KNTC1 on cervical neoplasm through in-vivo and in-vitro experiments, and speculated that it could mediate tumor invasion via MMP9 and MMP2." (PMID 35389773, 2022). "Four biomarkers had significantly higher expression levels in primary cervical tumors compared with normal cervical tissues: HPV16-E6 (p < 0.001), and CK19, uPA, and MMP9 (p < 0.05)." (PMID 29774091, 2018). "Moreover, cervical tumor cells may inhibit DC migration to lymph nodes through CCR7 depletion and induce DCs to produce matrix metalloproteinase 9 (MMP-9), further promoting tumor establishment." (PMID 39408687, 2024).
chronic hepatitis B (5 papers, 2013 to 2025). "This was similar to the role of MMP-9 in chronic hepatitis B patients and in oral keratinocytes, as well as MMP-14 in NSCLC patients." (PMID 33593275, 2021). "MMP-9/TIMP-1 complex was reported to be serum marker for fibrosis in children with chronic hepatitis B." (PMID 23672427, 2013). "Moreover, a significant elevation in plasma MMP9 levels was observed in patients with ACLF compared to those with chronic hepatitis B (CHB) and acute decompensated cirrhosis (AD)." (PMID 40070835, 2025).
congenital heart disease (5 papers, 2019 to 2025). A heart disease that is present at birth. "Indeed, the present study provides the first piece of evidence of elevated MMP-2 and MMP-9 in adolescents and adults with repaired congenital heart disease at risk of ascending aortopathy." (PMID 30655554, 2019). "Novel approaches, such as coating PTFE shunts with agents specifically suppressing pathways around EGF/EGFR and TIMP-1/MMP-9, might significantly reduce neointimal hyperplasia in SP shunts and therefore improve the outcome of children with complex and congenital heart defects." (PMID 36867212, 2023). "The results of our study and those of related studies indicate that MMP-2, MMP-9, TIMP-1, and according to our findings, also TIMP-2, play a role in the etiopathogenesis of VSD and other congenital heart anomalies in humans." (PMID 39466144, 2025). "Since the pathophysiology of neointimal hyperplasia in SP shunts of infants with complex congenital heart disease remains largely unknown, we aimed to identify the role of EGFR and MMP-9 in the formation of neointima in SP shunts." (PMID 36867212, 2023). "We also conclude that urinary concentration of MMP-9, along with echocardiographic and clinical findings, may be helpful for predicting the natural course of VSD and, thus, assist in creating the best follow-up and therapy plan for each patient with this congenital heart defect." (PMID 39466144, 2025).
cystitis (5 papers, 2013 to 2024). Inflammation of the urinary bladder. "Notably, increased urinary contents of MMP‐9 and neutrophil gelatinase‐associated lipocalin in children with acute cystitis were reported clinically." (PMID 39723046, 2024). "The uNGAL/MMP-9 complex has been reported to be related to the presence of cystitis in children, but in this study, the uNGAL/MMP-9 complex appeared not only to be present in samples from the PYU groups but also in samples from the RF without PYU group." (PMID 25160665, 2014). "The NGAL/MMP-9 complex was found to exist not only in the patients with cystitis, but also in the cases with renal injury." (PMID 25160665, 2014). "On the other hand, the secretion of MMP-9 was enhanced by presence of inflammatory cells and so the presence of cystitis might lead to false positive results and decrease specificity." (PMID 23672427, 2013).
diabetic neuropathy (5 papers, 2008 to 2024). A chronic, pathological complication associated with diabetes mellitus, where nerve damages are incurred due to diabetic microvascular injury involving small blood vessels that supply these nerves, resulting in peripheral and/or autonomic nerve dysfunction. "This study explores the biological mechanisms underlying diabetic neuropathy and the potential role of MMP-9, providing valuable insights into the pathophysiology of DFUs and potential therapeutic targets." (PMID 38422498, 2024). "MMP-9/2 underlies the mechanism of α-lipoic acid in diabetic neuropathy, providing a potential target for the development of novel analgesic and anti-inflammatory drugs." (PMID 34631222, 2021). "Furthermore, the gelatinase MMP-9 plays a crucial role in the pathogenesis of diabetic neuropathy through axonal demyelination, which is one of the risk factors for DFU." (PMID 38422498, 2024). "However, reducing MMP-9 can be a potentially helpful step in mitigating the risk and impact of diabetic neuropathy, particularly when combined with other appropriate treatment approaches." (PMID 38422498, 2024). "According to some studies, the gelatinase matrix metalloproteinase 9 (MMP-9) has been found to play a vital role in the demyelination of axons and the development of diabetic neuropathy in rodents." (PMID 38422498, 2024). "In the realm of diabetic neuropathy, MMP-9 is considered crucial in its progression and holds a potential target for treatment purposes." (PMID 38422498, 2024). "MMP-9 plays a role in increasing tissue inflammation, which is one of the contributing factors to diabetic neuropathy." (PMID 38422498, 2024). "In the present study we have targeted MMP-2 and MMP-9 overactivation in diabetic neuropathy using a known MMP-2 and MMP-9 inhibitor, minocycline with a non-selective COX inhibitor aspirin." (PMID 21593984, 2008). "In experimental diabetic neuropathy, the involvement of MMP-2 and MMP-9 has also been implicated." (PMID 34631222, 2021). "In this study, we hypothesized and have provided evidence that MMP-9 and MMP-2 in the dorsal root ganglion (DRG) and dorsal horn (DH) of the spinal cord may play an important role in the pathogenesis of diabetic neuropathy and associated DNP." (PMID 34631222, 2021). "Our study reveals a critical role for gelatinase MMP-9 and MMP-2 in myelin abnormalities and neuropathic pain in rodents with STZ-induced diabetic neuropathy." (PMID 34631222, 2021). "Gelatinases MMP-9 and MMP-2 play a critical role in the pathogenesis of diabetic neuropathy and may serve as a potential treatment target." (PMID 34631222, 2021). "The reduction of MMP-9 as the study objective may not be sufficient to completely prevent diabetic neuropathy, as this disease is highly complex and involves numerous factors." (PMID 38422498, 2024).